SERAC1 (serine active site containing 1)
Description:
Facilitates the transport of serine from the cytosol to the mitochondria by interacting with and stabilizing Sideroflexin-1 (SFXN1), a mitochondrial serine transporter, playing a fundamental role in the one-carbon cycle responsible for the synthesis of nucleotides needed for mitochondrial DNA replication. Plays an important role in the phosphatidylglycerol (PG) remodeling that is essential for both mitochondrial function and intracellular cholesterol trafficking. Specifically involved in the exchange of the sn-1 acyl chain from PG 16:0/18:1(9Z) (also known as 1-hexadecanoyl-2-(9Z-octadecenoyl)-sn-glycero-3-phospho-(1'-sn-glycerol)) to PG 18:0/18:1(9Z) (also known as 1-octadecanoyl-2-(9Z-octadecenoyl)- sn-glycero-3-phospho-(1'-sn-glycerol)), a step needed in the bis(monoacylglycerol)phosphate biosynthetic pathway. May have acyltransferase activity although the mechanism for PG remodeling has not been determined.
Synonyms: FLJ14917
Tractability: Antibody: UniProt predicts a signal peptide or a membrane-spanning region; its Gene Ontology location is reachable by antibodies, with medium confidence. PROTAC: ubiquitination databases record sites on it; its protein half-life has been measured.
Gene: Protein-coding gene on chromosome 6 (158,109,515 to 158,168,295, reverse strand). Ensembl gene ENSG00000122335.
Subcellular location: Mitochondrion membrane; Endoplasmic reticulum; Mitochondrion
Gene Ontology:
Biological process: intracellular cholesterol transport; phosphatidylglycerol acyl-chain remodeling
Cellular component: endoplasmic reticulum; mitochondria-associated endoplasmic reticulum membrane contact site; mitochondrion; endoplasmic reticulum membrane; extracellular matrix; mitochondrial membrane; mitochondrial outer membrane
Genetic constraint (gnomAD): Loss-of-function variants: 32 observed, 63.12 expected, observed/expected ratio (o/e) 0.51, 90% interval 0.38 to 0.68. The upper end of that interval is the gene's LOEUF score, 0.68, which puts it in group 2 of 6, group 1 being the genes least tolerant of losing a copy. Missense variants: 512 observed, 676.41 expected, observed/expected ratio (o/e) 0.76, 90% interval 0.7 to 0.81. Synonymous variants: 197 observed, 231.68 expected, observed/expected ratio (o/e) 0.85, 90% interval 0.76 to 0.96.
Gene-disease validity (ClinGen):
ClinGen rates the evidence that SERAC1 causes each of these diseases.
Leigh syndrome (autosomal recessive): Definitive. A progressive neurological disease defined by specific neuropathological features associating brainstem and basal ganglia lesions.
Homologues: Orthologues: chimpanzee SERAC1 (99% identical), macaque SERAC1 (97% identical), dog SERAC1 (91% identical), rabbit SERAC1 (90% identical), pig SERAC1 (89% identical), guinea pig SERAC1 (88% identical), mouse Serac1 (87% identical), rat Serac1 (85% identical), tropical clawed frog serac1 (61% identical), zebrafish serac1 (61% identical), Drosophila melanogaster CG5455 (23% identical), Caenorhabditis elegans F17H10.1 (22% identical). Paralogues in human: POP1 (21% identical).
Diseases named in the same sentence as SERAC1 in open-access papers:
SERAC1 is named in the same sentence as 34 diseases in open-access papers, as found by Europe PMC text mining. Sharing a sentence is not in itself a finding about the gene and the disease. The quoted sentences say what the papers report.
Encephalopathy (15 papers, 2015 to 2025). Encephalopathy is a term that means brain disease, damage, or malfunction. "MEGDEL syndrome, a rare autosomal recessive disorder characterized by 3-methylglutaconic aciduria, deafness, encephalopathy, and Leigh-like syndrome, results from mutations in the SERAC1 gene." (PMID 38559521, 2024). "Recessive mutations in SERAC1 induce 3-methylglutaconic aciduria, deafness, encephalopathy, and neuroimaging evidence of Leigh-like disease (MEGDEL) syndrome." (PMID 33426505, 2020). "Case 4 was genetically diagnosed with SERAC1 gene mutation, which caused 3-methylglutaconic aciduria with deafness, encephalopathy, and Leigh-like syndrome." (PMID 32411386, 2020). "MEGDHEL syndrome, caused by a SERAC1 gene defect, is clinically defined as the association of 3‐MGA‐uria (MEG), deafness (D), hepatopathy (H), encephalopathy (E), and Leigh‐like features (L)." (PMID 40365324, 2025). "3-methylglutaconic aciduria with deafness-dystonia, hepatopathy, encephalopathy, and Leigh-like syndrome (MEGD(H)EL) syndrome is a rare autosomal recessive disease caused by variants in the serine active site containing 1 (SERAC1) gene." (PMID 41458770, 2025). "Mutations in the serine active site-containing protein 1 (SERAC1) gene cause MEGDEL syndrome [3-methylglutaconic aciduria (MEG), deafness (D), encephalopathy (E), Leigh-like syndrome (L)." (PMID 39592976, 2024). "3‐Methylglutaconic aciduria, dystonia–deafness, hepatopathy, encephalopathy, Leigh‐like syndrome (MEGDHEL) syndrome is caused by biallelic variants in SERAC1." (PMID 29205472, 2017). "Variants in human SERAC1 are associated with a spectrum of disorders, including MEGDHEL syndrome (3-methylglutaconic aciduria with deafness–dystonia, hepatopathy, encephalopathy, and Leigh-like syndrome), juvenile-onset complicated spastic paraplegia, and adult-onset generalized dystonia." (PMID 39596578, 2024). "Similarly, variants in SERAC1 are thought to cause a severe Mendelian phenotype (MEGDEL syndrome), which includes encephalopathy, dystonia and deafness." (PMID 26173456, 2015).
deafness (13 papers, 2015 to 2025). An inherited or acquired condition characterized by the complete loss of the ability to hear from one or both ears. "SERAC1 mutations impair mitochondrial respiration and intracellular cholesterol trafficking causing dystonia and deafness." (PMID 35684429, 2022).
MEGDEL syndrome (10 papers, 2015 to 2025). "The main finding of the study was that SERAC1 variants not only can lead to MEGDEL syndrome but also can cause cHSP." (PMID 35223715, 2021). "To date, increasing evidence has confirmed the relationship between MEGDEL syndrome and SERAC1 variants." (PMID 35223715, 2021). "Even rarer disorders are linked to MERCs defects; for example, the MEGDEL syndrome caused by mutated serine active site-containing protein 1 (SERAC1)." (PMID 32646031, 2020). "An abnormal fatty acid composition of phosphatidylglycerol and decreased bis(monoacylglycero)phosphate (BMP) concentration have been found in patients with MEGDEL syndrome and SERAC1 deficiency." (PMID 25778941, 2015). "Later, MEGDEL syndrome was associated with SERAC1 pathogenic mutations." (PMID 40365324, 2025). "In this study, we present a case from a Chinese family with disordered metabolism and dystonia owing to SERAC1 variants; the clinical phenotypes of the proband were different from those of MEGDEL syndrome but were similar to those juvenile-onset complicated hereditary spastic paraplegia." (PMID 35223715, 2021). "Previous studies have identified a causal relationship between SERAC1 variants and MEGDEL syndrome." (PMID 35223715, 2021). "The serine active site-containing protein 1 (SERAC1) biallelic variant usually causes MEGDEL syndrome, clinically characterized by increased excretion of 3-methylglutaconic in the urine, muscle hypotonia, sensorineural deafness, and Leigh-like lesions on brain MRI scans." (PMID 35223715, 2021). "Furthermore, hepatopathy is also a relatively common feature in MEGDEL syndrome with SERAC1 deficiency, which involves lipid metabolism." (PMID 25778941, 2015).
Dystonia (5 papers, 2015 to 2025). An abnormally increased muscular tone that causes fixed abnormal postures. "The adult-onset disease associated with SERAC1 deficiency is characterized by cognitive regression and progressive dystonia beginning in early adulthood." (PMID 39596578, 2024). "All of the human SERAC1 deficiency disorders are characterized by dystonia, which is the most prominent sign in the canine disease." (PMID 39596578, 2024).
breast carcinoma (3 papers, 2011 to 2022). "The increased expression of NSUN4 and SERAC1 has been described in breast cancer." (PMID 36466711, 2022). "Each of the three TAAs, ASB-9 (36/87 (41.3%), P = .0112), SERAC1 (41/87 (47.1%), P = .0009), and RELT (46/87 (52.9%), P = .0001) elicited significantly higher frequency of AAbs in breast carcinoma patients compared to healthy controls." (PMID 21423545, 2011). "Thus, the absence of SERAC1 in our SFXN1 interactome may be explained by either the different cell lines used (mammary tumor cells versus kidney embryonic cells) or a labile interaction that could not be detected with endogenous SFXN1." (PMID 36138777, 2022).
acute liver failure (2 papers, 2016 to 2024). Rapid deterioration of liver function causing encephalopathy and coagulopathy. "Another study performed whole exome sequencing in three children with acute liver failure and identified pathogenic mutations in MPV17, SERAC1 and NOTCH2, despite the lack of characteristic clinical phenotypes for these genes." (PMID 27053192, 2016).
Hearing impairment (2 papers, 2016 to 2022). A decreased magnitude of the sensory perception of sound. "Ex post it was apparent that earlier some important clinical features, including hearing impairment in the patient with SERAC1 mutations and increased excretion of 3-MGA in the terminal stage in the boy with the TAZ mutation, had been overlooked." (PMID 27290639, 2016).
cognitive delay (1 paper, 2024). "A juvenile-onset disorder associated with SERAC1 deficiency is characterized by cognitive delay and slowly progressive lower limb spasticity beginning in adolescence." (PMID 39596578, 2024).
Failure to thrive (1 paper, 2025). Failure to thrive (FTT) refers to a child whose physical growth is substantially below the norm. "This case report raises awareness for an atypical presentation of MEGDHEL syndrome associated with a homozygous nonsense variant of SERAC1 clinically characterized by mild hypertransaminasemia, failure to thrive, no neurological involvement, and starting in early childhood rather than infancy." (PMID 40365324, 2025). "We report an atypically mild phenotype of MEGDHEL syndrome, beginning in early childhood and characterized by failure to thrive, mild hypertransaminasemia, and 3‐MGA‐uria, without neurologic involvement, associated with a novel variant in the SERAC1 gene." (PMID 40365324, 2025).
hereditary spastic paraplegia (1 paper, 2021). Hereditary spastic paraplegias (HSP) comprise a genetically and clinically heterogeneous group of neurodegenerative disorders characterized by progressive spasticity and hyperreflexia of the lower limbs. "This study presented a patient with complicated hereditary spastic paraplegia caused by SERAC1 variants." (PMID 35223715, 2021). "However, SERAC1 variants have been found to cause juvenile-onset complicated hereditary spastic paraplegia (cHSP) as well." (PMID 35223715, 2021).
Obesity (1 paper, 2025). Accumulation of substantial excess body fat. "To date, 4 key lipid metabolism regulators have been extensively investigated in obesity research: PPAR, CD36, serine active site-containing 1 (SERAC1), and adiponectin (ADPN)." (PMID 41345744, 2025).
Spastic paraplegia (1 paper, 2021). Complete loss of the ability to move the lower limbs accompanied by spasticity of the lower limbs. "Thus, in this study, we aimed to confirm the relationship between SERAC1 variants and complicated hereditary spastic paraplegia." (PMID 35223715, 2021).
mitochondrial disease (2 papers, 2016 to 2019). "In two subjects [P28 and P37] we found mutations in TAZ and SERAC1 genes known to cause mitochondrial diseases with 3-MGA as a discriminative feature." (PMID 27290639, 2016).
cancer (1 paper, 2022). A tumor composed of atypical neoplastic, often pleomorphic cells that invade other tissues. "SERAC1 also has a strong interaction with multiple splicing factors (hnRNP A3, hnRNP J, hnRNP G, FMRP, Fox-2) in the context of cancer prognosis and development." (PMID 35589867, 2022). "In addition, 1 SNP was detected in KMT2C, a BC oncogene, and 9 others were detected in or near 10 genes (SERAC1, DAGLB, MACF1, NVL, FBXW4, FANK1, KCTD4, CAVIN1; ATP6V0A1 and ZBTB20-AS1) previously associated with non-BC cancers." (PMID 35589867, 2022).
metabolic disease (1 paper, 2014). A congenital disorder (due to inherited enzyme abnormality) or acquired (due to failure of a metabolically important organ) disorder resulting from an abnormal metabolic process. "This lipase domain is found in the human SERAC1 protein, which was found to be involved in a metabolic disease." (PMID 25398782, 2014).
SERAC1 also shares sentences with these, for which no sentence is quoted: hepatopathy (7 papers); 3-methylglutaconic aciduria (5); 3-methylglutaconic aciduria with deafness, encephalopathy, and Leigh-like syndrome (1); autism (1); cardiomyopathy (1); cholestasis (1); Encephalomyopathies (1); genetic disorders (1); glioma (1); Hyperammonemia (1); Hypoglycemia (1); lactic acidosis (1); Leigh syndrome (1); movement disorder (1); neurological disorders (1); Onset (1); primary ciliary dyskinesia (1); trichothiodystrophy (1); Tumor (1).